NXNL2 (nucleoredoxin like 2)
Description:
May be involved in the maintenance of both the function and the viability of sensory neurons, including photoreceptors and olfactory neurons.
Synonyms: RdCVF2; C9orf121; RdCVF2L
Tractability: No criterion of Open Targets' tractability assessment is met for any kind of drug.
Gene: Protein-coding gene on chromosome 9 (88,534,033 to 88,584,274, forward strand). Ensembl gene ENSG00000130045.
Subcellular location (Human Protein Atlas): Cytosol
Gene Ontology:
Biological process: sensory perception of smell; visual perception; photoreceptor cell maintenance; sensory perception
Genetic constraint (gnomAD): Loss-of-function variants: 7 observed, 9.55 expected, observed/expected ratio (o/e) 0.73, 90% interval 0.42 to 1.37. That is too few expected variants to judge how well the gene tolerates losing a copy. Missense variants: 233 observed, 210.65 expected, observed/expected ratio (o/e) 1.11, 90% interval 0.99 to 1.23. Synonymous variants: 109 observed, 97.82 expected, observed/expected ratio (o/e) 1.11, 90% interval 0.95 to 1.31.
Homologues: Orthologues: chimpanzee NXNL2 (99% identical), mouse Nxnl2 (85% identical), pig NXNL2 (84% identical), rat Nxnl2 (83% identical), guinea pig NXNL2 (81% identical), dog NXNL2 (76% identical), macaque NXNL2 (66% identical), zebrafish nxnl2 (62% identical), tropical clawed frog nxnl2 (59% identical), Caenorhabditis elegans R05H5.3 (34% identical), Caenorhabditis elegans trx-3 (25% identical). Paralogues in human: NXN (33% identical), NXNL1 (31% identical).
Diseases named in the same sentence as NXNL2 in open-access papers:
NXNL2 is named in the same sentence as 3 diseases in open-access papers, as found by Europe PMC text mining. Sharing a sentence is not in itself a finding about the gene and the disease. The quoted sentences say what the papers report.
tumor (2 papers, 2007 to 2021). "Likewise, the following marker genes were selected for analysis in PF tumours: LAMA2, ALDH1L1, SLC6A13, IGSF1, and CXorf67 for PFA; and NELL2, DNAH1, CEP83, C9orf72, and NXNL2 for PFB tumours." (PMID 34314101, 2021).
NXNL2 also shares sentences with these, for which no sentence is quoted: neuroblastoma (1 paper); retinoschisis (1).